FAM138B (family with sequence similarity 138 member B)
Synonyms: F379; bA395L14.6
Gene: Long non-coding RNA gene on chromosome 2 (113,541,518 to 113,578,852, forward strand). Ensembl gene ENSG00000226516.
Diseases named in the same sentence as FAM138B in open-access papers:
FAM138B is named in the same sentence as 4 diseases in open-access papers, as found by Europe PMC text mining. Sharing a sentence is not in itself a finding about the gene and the disease. The quoted sentences say what the papers report.
hepatocellular carcinoma (1 paper, 2020). A malignant tumor that arises from hepatocytes. "A recent study indicated that linc-FAM138B was related to the development and prognosis of HBV-related hepatocellular carcinoma." (PMID 33401249, 2020).
lung adenocarcinoma (1 paper, 2020). A carcinoma that arises from the lung and is characterized by the presence of malignant glandular epithelial cells. "LncRNA FAM138B (linc-FAM138B) was first found to be a diagnostic and prognostic biomarker in lung adenocarcinoma." (PMID 33401249, 2020).
cancer (1 paper, 2020). A tumor composed of atypical neoplastic, often pleomorphic cells that invade other tissues. "Then, we detected the linc-FAM138B level in exosomes from normal and cancer cells, which showed that linc-FAM138B was lower expressed in cancer cells of HCC." (PMID 33401249, 2020). "And we isolated exosomes from cancer cells after transfection, the expression of linc-FAM138B was upregulated in exosomes after linc-FAM138B plasmid transfection." (PMID 33401249, 2020). "Our study revealed that exo-linc-FAM138B secreted by cancer cells inhibited HCC development via targeting miR-765, which provided a new idea and perspective for in-depth understanding of the complex signal regulation in HCC process." (PMID 33401249, 2020). "In conclusion, exo-linc-FAM138B secreted by cancer cells inhibited HCC development via targeting miR-765, which provided a new idea and perspective for in-depth understanding of the complex signal regulation in HCC process." (PMID 33401249, 2020). "To evaluate the role of exosomal-linc-FAM138B (exo-FAM138B) in HCC development, we transfected linc-FAM138B plasmid or its NC into cancer cells." (PMID 33401249, 2020). "Interestingly, present data found that linc-FAM138B was packaged into cancer cells of HCC, and exo-FAM138B could be transmitted in to HCC cell lines." (PMID 33401249, 2020). "Interestingly, linc-FAM138B could be packaged into cancer cells." (PMID 33401249, 2020). "We then transfected siRNA of linc-FAM138B (si-FAM138B) into cancer cells from HCC tissues, and exosomes was isolated from cancer cells after transfection." (PMID 33401249, 2020). "Together, linc-FAM138B could be enveloped into exosomes of cancer cells in HCC patients, and exosome from cancer cell transmitted linc-FAM138B to HCC cell lines." (PMID 33401249, 2020). "Present study showed that linc-FAM138B was down-regulated in HCC tissues, and linc-FAM138B could be enveloped into exosomes from cancer cells." (PMID 33401249, 2020).
tumor (1 paper, 2020). "Exo-FAM138B injection decreased tumor volume, and inhibited the ratio of tumor weight to body weight." (PMID 33401249, 2020). "Together, exo-FAM138B secreted by MSCs promoted tumor progression in TNBC cells." (PMID 33401249, 2020). "In addition, isolated tumor tissues had a higher linc-FAM138B level after exo-FAM138B injection." (PMID 33401249, 2020).